TH (tyrosine hydroxylase)
Description:
Catalyzes the conversion of L-tyrosine to L-dihydroxyphenylalanine (L-Dopa), the rate-limiting step in the biosynthesis of catecholamines, dopamine, noradrenaline, and adrenaline. Uses tetrahydrobiopterin and molecular oxygen to convert tyrosine to L-Dopa (PubMed:15287903, PubMed:1680128, PubMed:17391063, PubMed:24753243, PubMed:34922205, PubMed:8528210, Ref.18). In addition to tyrosine, is able to catalyze the hydroxylation of phenylalanine and tryptophan with lower specificity (By similarity). Positively regulates the regression of retinal hyaloid vessels during postnatal development (By similarity). [Isoform 5]: Lacks catalytic activity. [Isoform 6]: Lacks catalytic activity.
Synonyms: TYH; DYT5b; DYT14
Tractability: Small molecule: an approved drug acts on it; a structure with a bound ligand is known; it has a binding pocket of medium quality; it belongs to a druggable protein family. PROTAC: a small molecule that binds it is known.
Target class: Enzyme; Oxidoreductase
Safety:
Unwanted effects reported when the protein is acted on. In parentheses: how it was acted on, where the effect was seen, and who reports it.
opioid dependence (source: ClinPGx)
Gene: Protein-coding gene on chromosome 11 (2,163,929 to 2,171,968, reverse strand). Ensembl gene ENSG00000180176.
Subcellular location: Cytoplasm, perinuclear region; Nucleus; Cell projection, axon; Cytoplasm; Cytoplasmic vesicle, secretory vesicle, synaptic vesicle
Subcellular location (Human Protein Atlas): Cytosol
Pathways (Reactome):
Metabolism: Catecholamine biosynthesis
Gene Ontology:
Molecular function: enzyme binding; protein binding; tyrosine 3-monooxygenase activity; iron ion binding; monooxygenase activity; oxidoreductase activity, acting on paired donors, with incorporation or reduction of molecular oxygen, reduced pteridine as one donor, and incorporation of one atom of oxygen
Biological process: dopamine biosynthetic process; epinephrine biosynthetic process; norepinephrine biosynthetic process; response to ethanol; response to hypoxia; anatomical structure morphogenesis; animal organ morphogenesis; cognition; dopamine biosynthetic process from tyrosine; embryonic camera-type eye morphogenesis; eye photoreceptor cell development; heart development; heart morphogenesis; hyaloid vascular plexus regression; learning; locomotory behavior; mating behavior; memory; pigmentation; regulation of heart contraction; synaptic transmission, dopaminergic; visual perception; aromatic amino acid metabolic process; catecholamine biosynthetic process
Cellular component: cytoplasm; cytoplasmic side of plasma membrane; cytoplasmic vesicle; melanosome membrane; neuron projection; nucleus; smooth endoplasmic reticulum; axon; cytosol; perikaryon; perinuclear region of cytoplasm; synaptic vesicle
Genetic constraint (gnomAD): Loss-of-function variants: 49 observed, 48.96 expected, observed/expected ratio (o/e) 1, 90% interval 0.8 to 1.27. The upper end of that interval is the gene's LOEUF score, 1.27, which puts it in group 5 of 6, group 1 being the genes least tolerant of losing a copy. Missense variants: 720 observed, 648.1 expected, observed/expected ratio (o/e) 1.11, 90% interval 1.04 to 1.18. Synonymous variants: 330 observed, 279.37 expected, observed/expected ratio (o/e) 1.18, 90% interval 1.08 to 1.29.
Gene-disease validity (ClinGen):
ClinGen rates the evidence that TH causes each of these diseases.
tyrosine hydroxylase deficiency (autosomal recessive): Definitive. Tyrosine hydroxylase (TH) deficiency is an autosomal recessive disorder characterized by a spectrum of phenotypic features, based on severity and response to levodopa.
Homologues: Orthologues: chimpanzee TH (99% identical), macaque TH (99% identical), guinea pig TH (90% identical), dog TH (90% identical), rat Th (89% identical), mouse Th (88% identical), pig TH (87% identical), tropical clawed frog th (74% identical), zebrafish th (68% identical), Drosophila melanogaster ple (48% identical), Caenorhabditis elegans cat-2 (42% identical). Paralogues in human: TPH2 (46% identical), PAH (45% identical), TPH1 (44% identical).
Diseases named in the same sentence as TH in open-access papers:
TH is named in the same sentence as 285 diseases in open-access papers, as found by Europe PMC text mining. Sharing a sentence is not in itself a finding about the gene and the disease. The quoted sentences say what the papers report.
Parkinson disease (302 papers, 2008 to 2026). A progressive degenerative disorder of the central nervous system characterized by loss of dopamine producing neurons in the substantia nigra and the presence of Lewy bodies in the substantia nigra and locus coeruleus. "The level of deficiency of tyrosine hydroxylase (TH) explains the phenotype varying from mild (dystonia) to severe (parkinsonism with motor delay) to very severe (progressive infantile encephalopathy)." (PMID 41179085, 2025). "In the IF experiments using the TH antibody, we observed that, in comparison to the normal group, Parkinson’s disease mice had a more substantial loss of dopamine neurons and their projection fibers." (PMID 41195080, 2025). "The striatum has been reported to be a region enriched with tyrosine hydroxylase (TH)-expressing dopaminergic neurons, which are implicated in the pathogenesis of Parkinson’s disease (PD)." (PMID 40565229, 2025). "ClinVar data showed only two gene mutations in TH, but that these had an uncertain association with Parkinson’s pathogenesis." (PMID 40422884, 2025). "For comparison, as Parkinson’s disease is characterized by very low levels and dysregulated TH, it has been termed a TH deficiency syndrome." (PMID 39619336, 2024). "Rapamycin treatment in different mouse models of Parkinson’s disease prevented the loss of tyrosine hydroxylase (TH+) neurons in the substantia nigra densa and improved muscle coordination, with excellent preventive effects." (PMID 37450933, 2024). "When TH was found dysfunction, and therefore result in the deficiency of the DA synthesis, which ultimately leads to Parkinsonism." (PMID 38610044, 2024). "In a Pitx3-deficient mouse model, which mimics the loss of dopaminergic neurons seen in Parkinson’s disease, Ser40 phosphorylation remained manipulable despite reduced tyrosine hydroxylase protein levels." (PMID 39456033, 2024). "It was shown that kaempferol, identified in the extract, act as neuroprotective agent against rotenone-induced Parkinson’s disease model of rats by preventing the loss of tyrosine hydroxylase expression." (PMID 36968491, 2023). "A 45 nucleotide G-quadruplex sequence present in the promoter region of tyrosine hydroxylase (TH) can regulate transcription and has been linked with neurological and psychological disorders such as Parkinson’s and schizophrenia." (PMID 36980918, 2023). "Immunohistological examination of tyrosine hydroxylase (TH) confirmed the loss of DaNs in the macaque model of parkinsonism (p < 0.0001)." (PMID 37980356, 2023). "Parkinson’s disease is a progressive neurodegenerative disorder characterized by the preferential loss of tyrosine hydroxylase (TH)-expressing dopaminergic neurons in the substantia nigra." (PMID 36371400, 2022). "Inactivation of tyrosine hydroxylase is closely associated with degeneration of the substantia nigra state and is a classic motor feature of Parkinson’s disease." (PMID 36235835, 2022). "Tyrosine hydroxylase (TH) catalyzes the rate-limiting step in the biosynthesis of dopamine (DA) and other catecholamines, and its dysfunction leads to DA deficiency and parkinsonisms." (PMID 35013193, 2022). "The main symptoms of Parkinson’s disease are tremor, rigidity, and bradykinesia, all of which are caused by the degeneration of tyrosine hydroxylase positive dopaminergic neurons in the substantia nigra." (PMID 35458680, 2022). "Mir-133b regulates production of tyrosine hydroxylase and the dopamine transporter, and is involved in the degeneration of the nigrostriatal dopaminergic system, which is the cause of Parkinson’s disease." (PMID 36613744, 2022). "The TH marker has been used in postmortem studies to quantify the degree of dopaminergic cell loss in Parkinson’s patients." (PMID 36233034, 2022). "These biochemical characteristics of TH are hypothetically involved in the loss of dopaminergic neuronal function in Parkinson’s disease." (PMID 33429895, 2021).
Parkinson disease (continued). "In vivo MPTP-induced PD mouse investigations demonstrate that MEs prevent MPTP-induced neuron loss in the substantia nigra and improve parkinsonism in MPTP-treated mice by increasing the expression level of TH and downregulating α-synuclein protein expression." (PMID 33505591, 2021). "Nurr1 activates tyrosine hydroxylase (TH) gene expression via direct binding to its promoter, and Nurr1 gene defect is associated with Parkinson's disease." (PMID 35087379, 2021). "The classically described motor symptoms of Parkinson’s disease result from the loss of tyrosine hydroxylase (TH) positive dopaminergic (A9) neurons of the substantia nigra pars compacta." (PMID 34941945, 2021). "We also introduce the relation of α-synuclein propagation with the loss of TH protein in Parkinson’s disease as well as anticipate therapeutic targets and early diagnosis of these diseases." (PMID 32471089, 2020). "In Parkinson’s disease, dysfunction of the nigrostriatal tract begins with an initial loss of TH expressing nigrostriatal axon terminals and is followed by actual loss of dopaminergic neurons in the substantia nigra." (PMID 32977825, 2020). "Equine PPID shares similar neurochemical perturbations observed in Parkinson’s disease including oxidative stress, antioxidant deficiency, nitrated α-synuclein accumulation and loss of TH immunoreactivity." (PMID 32977825, 2020). "A recent post-mortem study showed that within 4 years post-diagnosis, patients with Parkinson’s disease had an almost complete loss of TH-positive terminals and dopamine transporter immunohistochemistry in the dorsal putamen." (PMID 30808022, 2019). "Neurodegenerative diseases involve loss of specific neuron types, such as the midbrain tyrosine hydroxylase-positive dopamine neurons in Parkinson's disease and in animal models of nigrostriatal degeneration." (PMID 29276478, 2017). "Here we describe a unique case of DRD and possible parkinsonism due to TH deficiency with residual symptoms of dystonia that was task dependent and responded to a sensory trick." (PMID 29225908, 2017). "Mutations in Nurr1 have been linked to Parkinson’s disease and Nurr1 is reduced in patients with Parkinson’s disease and correlates with the loss of tyrosine hydroxylase immunoreactivity." (PMID 28989991, 2017). "Injection of 6-OHDA into the striatum of laboratory animals produces acute parkinsonism characterized by defects in dopamine secretion and progressive loss of tyrosine hydroxylase (TH) positive neurons in the substantia nigra." (PMID 23818941, 2013). "The therapeutic efficacy of THLs was demonstrated in vivo in a model of Parkinson's disease (PD), wherein the therapeutic gene encoded for tyrosine hydroxylase (TH)." (PMID 22175028, 2011). "We define our model as early parkinsonism because we observed 50% loss in TH-positive neurons in SNpc (patients typically show 70% loss), and we observed consistent, robust, and specific motor deficits on the accelerating rotarod and in the hindlimb stepping task, only." (PMID 38786023, 2024). "Excess iron caused a decrease in the number of TH-ir neurons in the black substance due to oxidative stress and apoptosis and increased dopamine rotation in the striatum, which triggered the onset of Parkinson’s disease (PD)." (PMID 39795983, 2024). "High doses (HP) of perilla seed oil demonstrate efficacy in alleviating both motor and non‐motor symptoms of Parkinson's disease by reducing dopaminergic neuronal loss, upregulating tyrosine hydroxylase (TH), suppressing α‐synuclein and inflammatory responses, and modulating the gut–brain axis." (PMID 39554352, 2024). "NIT‐mediated tyrosinaemia in AKU may unmask Parkinson's disease in susceptible individuals by inhibition of brain tyrosine hydroxylase and thereby further decrease dopamine synthesis." (PMID 37404676, 2023).
Parkinson disease (continued). "Our findings suggest that the dopanization of α-synuclein by TH may contribute to oligomer and/or seed formation causing neurodegeneration with the potential to shed light on the pathogenesis of Parkinson’s disease." (PMID 36371400, 2022). "Immunohistochemical examination of TH‐positive dopaminergic neurons in the substantia nigra pars compacta is needed to clarify the loss of nigrostriatal dopaminergic neurons in the rotenone rat model of parkinsonism." (PMID 35068069, 2022). "The administration of VCE-003.2 to lipopolysaccharide (LPS)-lesioned mice (a model for Parkinson’s disease) attenuated the loss of tyrosine hydroxylase (TH)-containing nigrostriatal neurons, and in particular, the intense microgliosis caused by LPS in the substantia nigra." (PMID 33801057, 2021). "Parkinson disease is caused by loss of dopamine, which is synthesized from tyrosine by TH and DDC." (PMID 33673184, 2021). "Mutations in both alleles of TH have been associated with severe Parkinsonism-related phenotypes." (PMID 33013295, 2020). "Wheel running induces a significant elevation of dopaminergic fiber ramification and TH protein levels in spinal cord, and this may be a reason why some DEGs are associated with Parkinson’s disease." (PMID 30941019, 2019). "Because AR45 appears to be the predominant AR in the SNpc, it may have clinical relevance in the progressive motor disorder Parkinson’s disease (PD), resulting from the loss of TH+ neurons in the SNpc." (PMID 28856243, 2017). "PQ acts as a direct redox cycling agent to induce formation of free radicals and when administered to mice induces the cardinal symptoms of parkinsonism, including loss of TH+-positive dopaminergic (DA) neurons in the ventral midbrain's substantia nigra pars compacta (SNpc)." (PMID 22291891, 2012). "Increased activation of NFκB may contribute to the pathology in models of Parkinson's disease; therefore, it is possible that protection of striatal TH+ fibers by NAC treatment may be linked to reduced NFκB activity in these animals." (PMID 20808797, 2010). "Neuroproliferative and neuroprotective effects of VPA, for the DA system, have been reported previously, e.g., promoting TH expression in cultured neural progenitor cells and brain transplants or preventing the loss of dopaminergic neurons of SN in neurodegenerative models of parkinsonism." (PMID 32581730, 2020). "The reduction in TH in the dorsal striatum and loss of DA neurons and the presence of putative Lewy bodies in the SN in this phenotypic model recapitulating the neuropathology of Parkinson's disease is critical, and key to the characterization and relevance of this model to human PD." (PMID 24381808, 2013). "This case supports the importance of the TH gene in PD pathogenesis and raises more attention to rare variants in candidate genes being a risk factor for Parkinson disease." (PMID 20809526, 2010). "Taken together, these data imply that the likelihood bradykinesia occurring with aging may depend upon activity levels at a younger age, and nigral ser31 phosphorylation and TH protein levels could play a role in the inherent risk of developing aging-related Parkinsonism." (PMID 20037632, 2009). "In contrast to the loss of dopaminergic neurons in the midbrain, we observed an increase in tyrosine hydroxylase-positive neurons in the Parkinson’s disease olfactory bulb, suggesting a potential role for dopamine in the hyposmia associated with the condition." (PMID 40024917, 2025). "Automated cell detection method for TH-positive dopaminergic neurons in a mouse model of Parkinson’s disease using convolutional neural networks." (PMID 41294740, 2025). "Previous studies have reported that α-synuclein (α-Syn) plays a significant role in the pathology of Parkinson’s disease, while tyrosine hydroxylase (TH) is a well-established marker of dopaminergic neuronal integrity and function." (PMID 40999534, 2025).
Parkinson disease (continued). "Pathogenic variants of the J-domain protein DNAJC12 cause parkinsonism, which is associated with a defective interaction of DNAJC12 with tyrosine hydroxylase (TH), the rate-limiting enzyme in dopamine biosynthesis." (PMID 40113792, 2025). "The relative TH protein content (TH/internal reference protein) was significantly lower in Parkinson’s disease mice compared to normal mice." (PMID 41195080, 2025). "In post-mortem tissue from individuals with Parkinson’s disease, there is evidence that melanized dopamine neurons in the substantia nigra lose TH expression before undergoing neurodegeneration." (PMID 41279396, 2025). "Concurrently, exogenous CX3CL1 improved motor function in Parkinson's disease model mice with the Park7 knockout, promoting survival of tyrosine hydroxylase-positive neurons in the substantia nigra and reducing Iba-1-positive microglial activation." (PMID 40145975, 2025). "The interaction between HIF-1α and tyrosine hydroxylase (TH) forms a crucial bridge to understanding its role in Parkinson’s disease." (PMID 40999534, 2025). "The SH-SY5Y human neuroblastoma cell line is widely used as a Parkinson’s disease model due to its dopaminergic-like morphology and expression of key markers, including TH, dopamine-β-hydroxylase, and the DAT." (PMID 40430379, 2025). "In order to further investigate the effect of Safranal on pathological changes in Parkinson’s mouse, the content of DA and the expression of TH in the striatum were detected." (PMID 38683404, 2024). "When peripheral monocytes from healthy elderly subjects are exposed to TNF-alpha, tyrosine hydroxylase level increases as observed in monocytes from people with Parkinson’s disease." (PMID 38904783, 2024). "In human midbrain organoids bearing a Parkinson-driving LRRK2 mutation, a novel Nurr1 agonist rescued tyrosine hydroxylase expression highlighting the potential of the new Nurr1 modulator chemotype as lead and as a chemical tool for biological studies." (PMID 38951694, 2024). "In an animal model of Parkinson’s Disease, the overexpression of IL-1β in the caudate nucleus increases tyrosine hydroxylase immunoreactivity and behavioral outcome of the animals eight weeks after lesion." (PMID 38389906, 2024). "Activation of Shh signaling through the injection of active Shh protein in rodent or primate models of Parkinson’s disease has been shown to preserve TH immunoreactive neurons in the SN and dopaminergic axons in the striatum, improving motor function." (PMID 38329543, 2024). "For statistical analysis of MPTP–induced changes in α–Syn and TH in mice brain, we observed the improvement of parkinsonism in mice brain by oral administration of WEG." (PMID 39302939, 2024). "Both pre‐treatment and post‐treatment with caffeine were found to protect Parkinson's disease (PD) rats from rotenone‐induced damage by increasing TH expression." (PMID 39670604, 2024). "The process of mitochondrial fusion in dopaminergic and TH-positive neurons is disrupted by Parkinson’s disease, leading to higher ROS levels." (PMID 39170675, 2024). "In chronic cultures of human iPSCs from sporadic and DJ-1 mutant homozygous Parkinson’s disease, the oxidation level increased over 150–180 days and was blocked by metyrosine, an inhibitor of tyrosine hydroxylase." (PMID 38904783, 2024). "Our study highlights the therapeutic potential of modulating the endogenous dopamine biosynthesis pathway via tyrosine hydroxylase Ser40 phosphorylation as a strategy to ameliorate Parkinson’s disease symptomatology." (PMID 39456033, 2024). "As such, cyclic nucleotide-mediated signaling offers a dual approach in Parkinson's disease treatment, replenishing dopamine levels through tyrosine hydroxylase Ser40 phosphorylation to alleviate motor symptoms and concurrently promoting neuroprotection." (PMID 39456033, 2024).